OR10G7 (olfactory receptor family 10 subfamily G member 7)
Description:
Odorant receptor.
Synonyms: OR11-283
Tractability: Antibody: its Gene Ontology location is reachable by antibodies, with high confidence; UniProt places it where antibodies can reach, with medium confidence; UniProt predicts a signal peptide or a membrane-spanning region.
Gene: Protein-coding gene on chromosome 11 (124,036,013 to 124,041,325, reverse strand). Ensembl gene ENSG00000182634.
Subcellular location: Cell membrane
Pathways (Reactome):
Sensory Perception: Expression and translocation of olfactory receptors; Olfactory Signaling Pathway
Gene Ontology:
Molecular function: olfactory receptor activity; G protein-coupled receptor activity
Biological process: detection of chemical stimulus involved in sensory perception of smell; G protein-coupled receptor signaling pathway
Cellular component: plasma membrane; membrane
Genetic constraint (gnomAD): Missense variants: 211 observed, 249.37 expected, observed/expected ratio (o/e) 0.85, 90% interval 0.75 to 0.95. Synonymous variants: 102 observed, 109.22 expected, observed/expected ratio (o/e) 0.93, 90% interval 0.8 to 1.1.
Homologues: Orthologues: chimpanzee OR10G7 (96% identical), macaque OR10G7 (92% identical), mouse Or10g7 (87% identical), dog OR10G9C (85% identical), dog OR10G9 (85% identical), mouse Or10g9 (85% identical), rat Or10g9 (84% identical), mouse Or10g9b (84% identical), rat Or10g9b (83% identical). Paralogues in human: OR10G9 (90% identical), OR10G4 (89% identical), OR10G8 (88% identical), OR10G2 (56% identical), OR10G6 (54% identical), OR10D3 (53% identical), OR10G3 (52% identical), OR10S1 (52% identical), OR2D3 (48% identical), OR2F1 (45% identical), OR2F2 (45% identical), OR2D2 (45% identical), and 80 more.
Diseases named in the same sentence as OR10G7 in open-access papers:
OR10G7 is named in the same sentence as 1 disease in open-access papers, as found by Europe PMC text mining. Sharing a sentence is not in itself a finding about the gene and the disease.
OR10G7 shares sentences with these, for which no sentence is quoted: cancer (1 paper).